HECTD4 (HECT domain E3 ubiquitin protein ligase 4)
Diseases named in the same sentence as HECTD4 in open-access papers (continued):
Sharing a sentence is not in itself a finding about the gene and the disease.
tumor (5 papers, 2018 to 2025). "We demonstrate a tumor and metastasis suppressor role for HECTD4, a previously uncharacterized member of the HECT family of E3 ubiquitin ligases." (PMID 40768362, 2025). "A genome-wide CRISPR-inactivation screen identified the previously uncharacterized E3 ubiquitin ligase HECTD4, as a tumor and metastasis suppressor, with COX-2 as its major degradation target." (PMID 40768362, 2025). "Despite their high baseline tumorigenesis, MDA-MB-231 cells with shRNA-mediated HECTD4 knockdown (>80%) doubled in tumor size in immunosuppressed NSG mice, compared with sh-scramble controls (457.1 μg ± 118.1 vs. 204.9 μg ± 51.01, P = 0.0078)." (PMID 40768362, 2025). "PTCH1 alone does not result in a morphoeic phenotype being common to both mBCC and nodBCC; however, loss-of-function (as a potential tumour-suppressor gene) drivers FLNB and HECTD4 were identified as being morphoeic-specific." (PMID 41373535, 2025). "Taken together, the tumor and metastasis suppressor effect of HECTD4 is dependent on suppressing COX-2 activity." (PMID 40768362, 2025). "We identified HECTD4, a previously uncharacterized gene encoding a conserved potential homologous to E6AP C-terminus domain–containing ubiquitin transferase, as a potent tumor and metastasis suppressor." (PMID 40768362, 2025). "The expression level of HECTD4 decreased with increasing tumour grade, and patients with low expression had a worse prognosis than those with high expression in the TCGA datasets." (PMID 35031058, 2022). "Gene alterations associated with tumor grade progression in initial low grade tumors include FBN3, CIT and HECTD4." (PMID 29507699, 2018). "Similarly, HECTD4-KD cells contributed to >70% of metastatic tumor cells in the lungs and >90% in the liver." (PMID 40768362, 2025).
cancer (3 papers, 2024 to 2025). A tumor composed of atypical neoplastic, often pleomorphic cells that invade other tissues. "While most studies have focused on the inflammatory output of prostaglandins in cancer initiation, the specific anchorage-independent growth context in which HECTD4 regulates COX-2 expression indicates a distinct role in sustaining epithelial cancer cells as they circulate in the bloodstream." (PMID 40768362, 2025). "HECTD4 missense variants (p.Ala1955Thr) were consistently present across all malignant tumors, irrespective of histologic subtype, implying a broader role in malignant transformation." (PMID 41168812, 2025). "In addition, an interactive effect of LCD and HECTD4 rs11066280 on colorectal carcinogenesis was emphasized, which may be helpful for establishing diet plans regarding cancer prevention." (PMID 38523829, 2024). "In addition, we provide an understanding of the interaction effect of LCD and HECTD4 rs11066280 on CRC, which may be helpful for establishing diet plans regarding cancer prevention." (PMID 38523829, 2024).
HECTD4 also shares sentences with these, for which no sentence is quoted: coronary artery disease (2 papers); autism (1); celiac disease (1); cervical cancer (1); glioblastoma (1); head and neck cancer (1); hepatocellular carcinoma (1); Hyperglycemia (1); hyperuricemia (1); lung carcinoma (1); myocardial infarction (1); neurological disease (1); renal cell carcinoma (1); triple-negative breast carcinoma (1); type 1 diabetes (1).